AFP (alpha fetoprotein)
Diseases named in the same sentence as AFP in open-access papers (continued):
Sharing a sentence is not in itself a finding about the gene and the disease.
liver cirrhosis (continued). "There were markedly significant differences in the clinical features such as sex, age, symptoms, concomitant diseases (hepatitis B and liver cirrhosis), and abnormally elevated plasma AFP between the Epi-HAML and HCC groups (P < 0.001)." (PMID 30619742, 2018). "We found that low expression of NFATc1 in HCC was significantly associated with larger tumor size, advanced TNM stage, higher serum AFP levels, and liver cirrhosis." (PMID 30085405, 2018). "High FOXC2 expression was correlated with liver cirrhosis (P = 0.0296), poor differentiation (P = 0.0302), high serum AFP levels (P = 0.00078), and the Ki-67 labeling index (P = 0.0348)." (PMID 29801468, 2018). "HOXC6 expression was positively correlated with high AFP level, liver cirrhosis, larger tumor, vascular invasion and BCLC stage." (PMID 29348394, 2018). "Clinically, Rab27a was positively associated with serum alpha-fetoprotein (AFP) level, vascular invasion and liver cirrhosis." (PMID 29725020, 2018). "Our results demonstrated that low expression of NFATc1 was correlated with larger tumor size (P = 0.020), advanced TNM stage (P = 0.001), higher serum AFP levels (P = 0.021), and liver cirrhosis (P = 0.033)." (PMID 30085405, 2018). "The ASA score, cause of liver cirrhosis, location of the tumor, TNM stage, preoperative CEA/CA19-9/AFP, albumin, total bilirubin, alkaline phosphatase, alanine aminotransferase and prothrombin time all were not significant." (PMID 27942875, 2017). "In multivariate analysis, presence of liver cirrhosis, AFP ≥ 400 IU/mL, and prNLR ≥ 2.1 were identified to be statistically significant unfavorable factors for OS (p = 0.048, < 0.001, and 0.023, respectively)." (PMID 28199977, 2017). "In univariate analysis, age ≥ 60 years, presence of liver cirrhosis, AFP ≥ 400 IU/mL, and prNLR ≥ 2.1 were identified to be statistically significant unfavorable factors for OS (p = 0.035, 0.010, < 0.001, and 0.004, respectively)." (PMID 28199977, 2017). "In univariate analysis, tumor size, tumor number, vascular invasion, Edmondson grade, liver cirrhosis, AFP level, HBsAg, AST and prothrombin time were prognostic factors for both OS and DFS of BCLC-B/C patients." (PMID 29299157, 2017). "At the same time, multivariate Cox regression analysis identified AFP ≥ 400 ng/mL, multiple tumors, macroscopic vascular invasion, and liver cirrhosis as independent prognostic factors for OS and RFS." (PMID 28572700, 2017). "In multivariate analysis, female sex, presence of liver cirrhosis, AFP ≥ 400 IU/mL, and prNLR ≥ 2.1 were identified to be statistically significant unfavorable factors for local PFS (p = 0.006, 0.020, 0.016, and < 0.001, respectively)." (PMID 28199977, 2017). "In univariate analysis, age > 40 years, liver cirrhosis,AFP > 10 ng/mL, HBeAg negativity, and the additional N-glycosylation mutations were significantly associated with HCC in HBsAg/anti-HBs coexistent patients." (PMID 28977899, 2017). "Serum specimens and clinical data were collected from 201 HCC and 117 BLD (41 liver cirrhosis, 76 chronic hepatitis) patients with abnormal serum AFP levels." (PMID 29228649, 2017). "Univariate analysis identified tumor number ≥ 2 (p = 0.004), liver cirrhosis (p = 0.030), AFP ≥ 25 ng/ml (p = 0.002) and NLR ≥ 3 (p = 0.017) as significant prognostic factors for poor RFS." (PMID 26918355, 2016). "Multivariate analysis identified tumor number ≥ 2 (p = 0.001), liver cirrhosis (p = 0.045), AFP ≥ 25 ng/ml (P = 0.005) and NLR ≥ 3 (p = 0.008) as independent prognostic factors for poor RFS." (PMID 26918355, 2016). "These factors include CTSB expression, gender, age, tumor size, Serum HBsAg, serum AFP, tumor size, liver cirrhosis, stage, tumor recurrence, and tumor differentiation." (PMID 26896959, 2016).
liver cirrhosis (continued). "The best cutoff values for MDK and AFP to discriminate HCC cases from those with liver cirrhosis were 0.387 and 88.5 ng/mL, respectively, with sensitivities (92.5 versus 40%), specificities (83.3 versus 96.7%), and accuracies (88.5 versus 68.2%), respectively." (PMID 25737783, 2015). "Current diagnostic methods by radiological imaging and AFP serum analysis remain deficient for detecting HCC at early and surgically manageable stages in patients with liver cirrhosis." (PMID 26447841, 2015). "In a univariate analysis, the AFP level was related to significant risk for both OS and DFS, and liver cirrhosis was the only significant prognostic factor for OS." (PMID 26375549, 2015). "It is known that in the Asia Pacific, the majority of HCC patients have a background of liver cirrhosis, the specificity of typical imaging findings, combined with the criterion of AFP >400 ng/ml resulting in HCC diagnosis of close to 100%." (PMID 25649133, 2015). "Alpha-fetoprotein and ultrasonography tests are provided for men and women aged 40 years or older with chronic HBV or hepatitis C virus (HCV) infection, liver cirrhosis, or chronic liver disease of any cause." (PMID 25387237, 2014). "These factors include CTSL expression, gender, age, tumor size, Serum HBsAg, serum AFP, tumor size, liver cirrhosis, stage, tumor recurrence and tumor differentiation." (PMID 25384089, 2014). "Ascites, Child–Pugh class, liver cirrhosis, and serum AFP level were other predictors of TTP (P<0.05 for each)." (PMID 24817002, 2014). "An average increase in serum AFP level of >7 ng/mL per month is a useful tool for diagnosing HCC in patients with liver cirrhosis and imaging findings that imply presence of tumors, especially when the serum AFP level is >200 ng/mL." (PMID 24993566, 2014). "Screening strategies including alpha-fetoprotein (AFP) and ultrasound every 6 months in patients with liver cirrhosis have been recommended to detect HCC at earlier stages leading to effective treatment strategies." (PMID 27785253, 2013). "For diagnosis of early HCC, patients with liver cirrhosis are advised to undergo periodic screening of serum AFP concentration and liver ultrasound at 6-to 12-monthintervals." (PMID 22760167, 2012). "Patients with low AZGP1 expression had a higher tendency to have high level of serum AFP, liver cirrhosis, and poor tumor differentiation." (PMID 22625427, 2012). "Taken together, these results suggest that the balance between anti-AFP Th1 and Tc1 responses switches to an anti-AFP Tc1 response as liver cirrhosis progresses." (PMID 20087354, 2010). "In conclusion, these results suggest that anti-AFP Th1 responses are more likely to be present in an early disease stage, whereas anti-AFP Tc1 responses are more likely to be present when liver cirrhosis has developed." (PMID 20087354, 2010). "The progressive elevation of alpha fetoprotein ≥7 ng/mL/month in patients with liver cirrhosis is useful for the diagnosis of hepatocellular carcinoma in patients that do not reach αFP levels ≥200 ng/mL." (PMID 17288606, 2007). "Subgroup analyses were performed according to baseline AFP level and liver cirrhosis status." (PMID 41602381, 2026). "However, clinical characteristics such as age, hepatitis history, AFP, liver cirrhosis, multiple tumors, tumor encapsulation, and TNM stage were not directly linked to FTO expression." (PMID 40316995, 2025). "Meanwhile, serum AFP, whether there was liver cirrhosis, tumor size, and number of tumors were significantly correlated with TTR (serum AFP value = 0.044, P value for liver cirrhosis = 0.002, tumor size < 0.0001, tumor number < 0.0001)." (PMID 38500533, 2024). "We examined the associations between liver background characteristics (including HBV, HCV, and liver cirrhosis) and tumor characteristics (such as alphafetoprotein (AFP), tumor size, tumor differentiation, and microvascular invasion) with intratumoral TLS (iTLS)." (PMID 38887293, 2024).
liver cirrhosis (continued). "Both patients had their tumor marker levels determined and both showed very high AFP titters of 10,464 ng/mL and 2212 ng/mL, respectively, raising the suspicion of HCC since values > 400 ng/mL are considered diagnostic for patients with liver cirrhosis." (PMID 39064538, 2024). "These predictors included gender, LOS, smoking status, HBV status, hypertension, COPD status, asthma status, CKD status, diabetes, anemia, thrombopenia, ascites, pneumonia, liver cirrhosis, HE, portal vein invasion, microvascular invasion, N stage, T stage, therapy type and AFP." (PMID 38886455, 2024). "MDK was better than AFP in differentiating HCC patients from individuals with liver cirrhosis." (PMID 38247828, 2024). "Finally, MDK was proven to have superior performance compared with AFP in differentiating HCC patients from individuals with liver cirrhosis." (PMID 38247828, 2024). "Univariate analysis demonstrated there existed a significant correlation between liver cirrhosis, tumor number, tumor size and nuclear SNRNP70/AFP combination and OS (P value for liver cirrhosis = 0.001, tumor size < 0.0001, tumor number = 0.001 and nuclear SNRNP70/AFP combination = 0.003)." (PMID 38500533, 2024). "Additionally, the multivariate Cox regression analysis confirmed that serum AFP levels (P=0.049), liver cirrhosis (P<0.001), and high CENPB protein expression (P=0.014) were independent predictors of OS." (PMID 37925172, 2023). "Subsequent Logistic regression analysis showed that PC(16:0/16:0), PC(18:2/18:2) and SM(d18:1/18:1) were independent risk factors distinguishing AFP negative HCC from liver cirrhosis patients." (PMID 36845695, 2023). "The slightly increased AFP level, the atypical aspect of the nodule on MRI with gadoxetate disodium and the absence of other risk factors, except for the liver cirrhosis, were arguments against the diagnosis of HCC." (PMID 37488645, 2023). "Modest elevations of AFP levels (between 10 and 500 ng/mL and occasionally up to 1000 ng/mL) may also be seen in adult patients with hepatitis of any type or liver cirrhosis." (PMID 35484503, 2022). "ICC patients with HBV infection were 5 years younger and had a higher male-to-female ratio, higher proportions of AFP (≥20ng/ml), liver cirrhosis, incomplete tumor capsule, vascular tumor thrombus, and advanced BCLC stage compared to those without HBV infection." (PMID 35800051, 2022). "The survival rate of HCC is at most 5 years, which is still very low, partly because of the unsatisfactory results of conventional biomarkers (e.g., DPC, AFP and AFP-L3) that are often unable to distinguish between cancer and inflammatory diseases, such as chronic hepatitis or liver cirrhosis." (PMID 35625573, 2022). "The results suggest that preoperative alpha-fetoprotein level, liver cirrhosis, Child–Pugh score, portal venin tumor thrombus, microvascular invasion, and molecular level of SMPDL3A were independent risk factors affecting the overall survival of patients with HCC." (PMID 35686107, 2022). "In the present study, serum AFP yielded an ROC-AUC of 0.917 for HCC versus liver cirrhosis." (PMID 35845304, 2022). "In addition to DAA treatment, our subgroup analysis also found that liver cirrhosis, serum AFP, ALBI grade and microvascular invasion represented independent risk factors for recurrence in HCV-related HCC." (PMID 35208582, 2022). "The expression of AFP is elevated in liver cirrhosis and liver cancer." (PMID 33727662, 2021). "The most recent review summarized the exploration of the occurrence of HCC after antiviral therapy, and summarized the factors (i.e., male, liver cirrhosis, diabetes, AFP levels, high liver stiffness, and past history of HCC) that contribute to the higher incidence of HCC." (PMID 34568017, 2021). "Besides its role in HCC diagnosis, higher serum AFP levels are also observed in patients with hepatitis and liver cirrhosis." (PMID 33289529, 2021).
liver cirrhosis (continued). "The results of the χ2 analysis indicated that the miRNA-140 expression was significantly associated with BCLC stage (P = 0.036) but not with other factors, such as biological sex, age, drinking history, family history, BMI, AFP, liver cirrhosis, number of tumours, and PVTT." (PMID 33628799, 2021). "In addition to cholecystectomy, we also found that age, liver cirrhosis, serum AFP, diabetes, Child Pugh classification, number of tumors, tumor size, histological grade and microvascular invasion represented independent risk factors for HCC recurrence." (PMID 34945733, 2021). "However, the data obtained to date consistently indicate that miR-122 is downregulated in patients with HBV-associated HCC and related to tumor size, lymph node metastasis, TNM stage, pathological type, differentiation grade, liver cirrhosis, AFP, and HBV DNA." (PMID 34771525, 2021). "In addition, EV‐lnc85 showed a high diagnostic performance for differentiating both AFP‐positive (AUC 0.90) and AFP‐negative HCC (AUC 0.88) from liver cirrhosis patients." (PMID 34708589, 2021). "Data obtained using 401 blood samples from 208 HCC patients and 193 liver cirrhosis patients showed that sensitivity and specificity of the tests for AFP were 62% and 90.2%, for PIVKA-II were 51% and 91.2%, for OPN 46.2% and 80.3%, and for DKK1 50% and 80.8%, respectively." (PMID 33562077, 2021). "We investigated serum alpha-fetoprotein (AFP), protein induced by vitamin K absence or antagonist II (PIVKA-II) and glypican-3 (GPC-3) diagnostic accuracy for HCC detection and prediction in patients with liver cirrhosis of viral etiology under surveillance." (PMID 33142893, 2020). "In patients with liver cirrhosis, fluctuations in AFP levels may reflect the sudden onset of viral hepatitis, the deterioration of the potential liver disease, or the development of HCC." (PMID 32053643, 2020). "However, serum levels of these proteins were not significantly different between HCC patients with normal AFP and liver cirrhosis controls." (PMID 31979338, 2020). "Also, consistent with MRM findings, we identified that serum Trim22 was significantly reduced in HCC patients with normal AFP compared with liver cirrhosis controls." (PMID 31979338, 2020). "PKM2 expression was found in significant correlation with HCC tumor size (P = 0.013) and tumor grade (P = 0.035) rather than the other clinicopathological features including gender, age, HBV status, liver cirrhosis, AFP, ALT, tumor numbers, tumor capsule, and BCLC stage." (PMID 33193421, 2020). "In analyses stratified by age, sex, tumor capsule, tumor size, liver cirrhosis, HBsAg, AFP, ALT, AST, Child-Pugh, and BCLC stage, inclusion of a quadratic term for serum prealbumin in the Cox proportional hazard models revealed a linear correlation between serum prealbumin and all-cause mortality." (PMID 33505912, 2020). "Increased expression of LINC01134 is positively correlated with microvascular invasion and macrovascular invasion but not correlated with age, gender, hepatitis B surface antigen (HBs antigen), liver cirrhosis, alpha-fetoprotein (AFP), tumor size, and encapsulation." (PMID 32656205, 2020). "Of these, eight proteins, glypican 3 (GPC3), squamous cell carcinoma antigen (SCCA), haptoglobin, C3 precursor, seprase, hemoglobin subunit gamma, hemoglobin subunit alpha, and teneurin-3, showed higher relative peaks in HCC cases with normal AFP levels than the liver cirrhosis controls." (PMID 31979338, 2020). "After extensive profiling of protein expression in serum samples from HCC patients with normal AFP levels, as well as liver cirrhosis patients for a control, we identified 10 proteins that were significantly altered in HCC patients compared to controls among the 41 MRM-targeted proteins." (PMID 31979338, 2020). "Also, serum levels of Trim22 were significantly reduced in HCC patients with normal AFP compared to those with liver cirrhosis (p = 0.032)." (PMID 31979338, 2020).
liver cirrhosis (continued). "In the present study, except for the FIB-4 index, we also showed that DM, liver cirrhosis, tumor size, histology stage, and vascular invasion were important predictors for HCC recurrence; in addition, DM, AFP, and histology stage were independent risk factors for overall survival." (PMID 31885547, 2019). "Furthermore, the nomogram constructed with HBV-related parameters harvested preoperatively including HBV DNA, liver cirrhosis, AFP, and BCLC stage accurately predicted an unfavorable postoperative prognosis." (PMID 31179237, 2019). "Moreover, hypomethylation status was associated with several clinical characteristics, such as male patients, higher AFP values, higher age of onset, fibrous capsules, tumor necrosis, liver cirrhosis, and tumor thrombus (P < 0.05)." (PMID 30575322, 2019). "Furthermore, Serum exosomal miR-122, miR-148a combined with alpha-fetoprotein (AFP) were significantly distinguish early HCC from liver cirrhosis, additionally, miR-122 was the best for differentiating HCC from healthy subjects." (PMID 30616541, 2019). "However, no significantly difference (P>0.05) was found between Wnt3a and HCC patients' age, gender, tumor size, AFP level, liver cirrhosis, or gross classification." (PMID 31737122, 2019). "However, no prognostic significance was found for the other characteristics including age, gender, HBsAg, HCV-Ab, liver cirrhosis, AFP, ALT, tumor encapsulation or differentiation." (PMID 31250351, 2019). "Of these patients, 74.1% had liver cirrhosis, and 71.9% were α-fetoprotein (AFP)-positive." (PMID 30126375, 2018). "However, we have not observed significant correlation between SPRY4-IT1 expression levels and other clinical characteristics such as age, gender, serum AFP level, HBsAg status, tumor size, liver cirrhosis and histological differentiation." (PMID 29214989, 2017). "Accumulated evidences showed that the clinical-pathological features were closely related to the prognosis of tumor, such as tumor size, tumor number, tumor stage, AFP level, lymph node metastasis, tumor thrombus, liver cirrhosis, vascular invasion and migration predicted poor prognosis for HCC." (PMID 29108386, 2017). "In multivariate logistic regression analyses, age > 40 years, AFP > 10 ng/mL, liver cirrhosis, HBeAg negativity, and the additional N-glycosylation mutations [OR, 2.831; 95% CI, 1.157−6.929; P = 0.023] were independent risk factors for the occurrence of HCC in HBsAg/anti-HBs coexistent patients." (PMID 28977899, 2017). "However, SNHG12 expression was not correlated with other clinicopathological variables such as gender, age, serum AFP, liver cirrhosis, PVTT and differentiation (P > 0.05)." (PMID 28073380, 2017). "In univariate analysis, female sex, presence of liver cirrhosis, AFP ≥ 400 IU/mL, pretreatment CP class B, and prNLR ≥ 2.1 were identified to be statistically significant unfavorable factors for local PFS (p = 0.028, 0.0015, 0.004, 0.035, and 0.001, respectively)." (PMID 28199977, 2017). "Previous study showed that serum Hp is highly expressed in HCC patients as compared with liver cirrhosis (LC) patients, suggesting that Hp could be another potential biomarker complementary to alpha-fetoprotein." (PMID 28158312, 2017). "However, the expression of PBLD was not significantly correlated with age, gender, hepatitis B surface antigen (HBsAg), hepatitis B e antigen (HBeAg), serum AFP level, liver cirrhosis, vascular invasion, intrahepatic metastasis, tumor number and tumor size." (PMID 26594798, 2016). "We evaluated the association between ECM1 expression and clinicopathological characteristics, including age, gender, tumor size, number of tumor nodules, tumor capsule, HBsAg status, serum AFP level, Edmondson’s grade, vascular invasion, Child-Pugh class, stage of liver cirrhosis, and TNM stage." (PMID 27460906, 2016).